CDK4 (cyclin dependent kinase 4)
Diseases named in the same sentence as CDK4 in open-access papers (continued):
Sharing a sentence is not in itself a finding about the gene and the disease.
cancer (continued). "Cyclin-Dependent Kinase 4/6 inhibitors are a newer class of cancer medications that can slow cancer growth by blocking proteins needed for cells to divide and are showing potential of being an additional therapeutic option for this cancer subtype." (PMID 40940886, 2025). "Overactivation of CDK4 and CDK6 kinases is associated with a loss of control over cell cycle regulation, contributing to cancer cell growth." (PMID 41375037, 2025). "The acquisition of resistance to ET and CDK4/6 inhibitors, like resistance to other cancer drugs, is a multi-step process involving progressive adaptations that can develop into long-term resistance." (PMID 40565304, 2025). "Non-clinical studies have demonstrated that the acquisition of resistance to ET and CDK4/6 inhibitors can involve early adaptations that allow cancer cells to escape growth inhibition." (PMID 40565304, 2025). "Our preclinical findings demonstrate that combining autophagy inhibitors, such as HCQ, with CDK4/6is induces irreversible growth arrest and establishes a stable state of cellular senescence in cancer cells." (PMID 39865083, 2025). "While several primary and secondary mechanisms of resistance have been previously identified, the molecular underpinnings of cancer resistance and progression to CDK4/6i remains to be elucidated in about half of the cases." (PMID 41279360, 2025). "Given the pivotal role of CDK4/6 deregulation in the pathogenesis of various malignancies, CDK4/6 inhibitors have been incorporated into cancer treatment protocols." (PMID 40856900, 2025). "Coadministration of autophagy inhibitors enhances the therapeutic efficacy of CDK4/6 inhibitors across a range of cancers, particularly in Rb-proficient and cyclin E-negative solid tumours." (PMID 40563591, 2025). "The key question is how the overexpressed CDK6 in cancer cells enables cell cycle progression in lieu of CDK4, and what molecular mechanisms differentiate the higher activity of CDK6 from that of CDK4." (PMID 40093074, 2025). "Encouragingly, in addition to their use in cancer treatment, CDK4/6 inhibitors are also being utilised to mitigate the side effects associated with traditional chemotherapy." (PMID 40563591, 2025). "The success of CDK4/6 inhibitors in HR+/HER2− breast cancer has prompted further research into their potential in other cancer types and combinations with targeted therapies, chemotherapy, and immunotherapy." (PMID 39813224, 2025). "While CDK4/6 inhibitors like Palbociclib are widely used to induce senescence in cancer cells, this is often accompanied by a robust SASP, including pro-inflammatory cytokines and interferon responses." (PMID 40766702, 2025). "The dysregulation of the CDK4/6 pathway is commonly observed in various cancers, leading to uncontrolled cell proliferation, making CDK4/6 a key therapeutic target in oncology." (PMID 40282469, 2025). "The overarching theme across these studies is CREPT’s universal role in promoting G1 phase progression through cyclin D1/CDK4/6 upregulation in various cancers." (PMID 40723282, 2025). "Both genetic and pharmacological inhibition of SP1 or SLC7A11 in experimental and clinical studies resulted in an improved response to CDK4/6is and a synergistic reduction in cancer proliferation." (PMID 40244377, 2025). "This light-controlled system allows spatiotemporal CDK4/6 degradation and G1 cell-cycle arrest, enabling a promising strategy to enhance specificity for cancer treatment and fundamental biological research." (PMID 40894871, 2025). "CDK4/6 inhibitors halt the cell cycle and inhibit cancer cell proliferation by selectively blocking the CDK4 and CDK6 proteins." (PMID 40287412, 2025).
cancer (continued). "Of note, the CDK4/6 inhibitor palbociclib, which is clinically used in adjuvant cancer therapy, reduced the expression of E2F1, MYBL2, and FOXM1 and of endoreduplications." (PMID 40319068, 2025). "Inhibitors targeting CDK4/6 have shown efficacy in arresting the cell cycle progression of cancer cells." (PMID 40316529, 2025). "We have also shown how autocrine estrogen signaling by intrinsically resistant cancer cells can provide transferable CDK4/6 inhibitor resistance to otherwise sensitive cells in the microenvironment." (PMID 40032842, 2025). "The improved disease-free survival rates in EBC with the integration of adjuvant CDK4/6 inhibitor therapy into clinical practice contribute to a rising workload for medical oncologists who are also facing a rising prevalence of cancer cases globally." (PMID 40710212, 2025). "Palbociclib (CDK4/6 inhibitor) was selected to directly induce cell cycle arrest, targeting the dysregulated cyclin D-CDK4/6-Rb pathway observed in various cancers." (PMID 41155905, 2025). "Nonetheless, cancer cells can circumvent the suppression of ERα via CDK4/6-mediated reactivation of downstream proliferative signals, providing a rationale for combined therapy." (PMID 40563591, 2025). "An increased activation of the PAM pathway is a common cancer cell adaptation that can contribute to resistance to BC treatment with ET and CDK4/6 inhibitors." (PMID 40565304, 2025). "Cyclin D kinase 4/6 (CDK4/6) specifically regulates the transition of cells from the G1 to S phase, and CDK4/6 inhibitors block this process and effectively block the proliferation of sensitive cancer cells." (PMID 40256431, 2025). "The discovery of alterations in the levels of the CDK4/6 pathway in the context of breast cell proliferation and cancer led to the discovery of new CDK4/6 inhibitors that have been dramatically modified for better BC therapy and the possibility for TNBC." (PMID 40282403, 2025). "EIF4A inhibition in cancer cells leads to G1-arrest through translation inhibition of CDK4, CDK6 or members of the cyclin D family." (PMID 38011999, 2024). "In silico analysis predicted Sil as the most potent anti-cancer and anti-proliferative drug against CDK4, altered in GBM." (PMID 39650055, 2024). "Regions that were significantly amplified in CS-like tumors held many genes known to be associated with cancer development, including KRAS, CDK4, and TERT." (PMID 38978078, 2024). "Despite the current success of CDK4/6 inhibitors, cancer therapy that targets cell cycle proteins is still in its infancy." (PMID 38605349, 2024). "Consistent with the cell line data, cancer organoids became more sensitive to HZ1 with the depletion of CDK4 or increased expression of Rb." (PMID 38963708, 2024). "As is the challenge with many anti-cancer drugs, resistance to CDK4/6 targeted therapies limits their use, ultimately leading to disease spread or relapse." (PMID 38831405, 2024). "Together, these data highlight the potential for inhibitors of Wnt signaling and cell cycle progression (i.e., CDK4/6 inhibitors) to be used for the treatment of Class 2/3 BRAF mutant cancers." (PMID 38275886, 2024). "As of the current knowledge cutoff, several clinical trials are likely underway or being planned to evaluate the safety and efficacy of CRISPR-Cas9 in editing the CDK4 gene in cancer patients." (PMID 38195537, 2024). "By blocking Rb phosphorylation, CDK4/6i induce G1 arrest and a phenotype resembling senescence in sensitive cancer cells." (PMID 38047585, 2024). "While sitravatinib treatment enhances the immune response in cooperation with abemaciclib, it also sensitizes the cancer cells to CDK4/6 inhibition by suppressing the RTKs—synergism through two complementary mechanisms." (PMID 38927958, 2024). "Erik’s report illustrate the complex nature of cancer cell cycles, genes (CDK4, CDK6, CCND1, CDK2, and CCNE1) that regulate the G1/S transition yield particularly variant vulnerabilities in different cancer cell." (PMID 38582921, 2024).
cancer (continued). "34.6% of patients received chemotherapy, whereas anti-HER2 therapy (17% of patients), anti-hormone therapy (15% of patients) and CDK4/6-inhibtor therapy (18% of patients) were the other most common anti-cancer therapies." (PMID 39415149, 2024). "Functional studies have shown its role in suppressing malignancy through its involvement in several pathways in cancer, where it mediates the regulation of critical genes, such as CDK4 and FOXM1." (PMID 39769441, 2024). "To elucidate the underlying mechanisms, we constructed an interpretable deep learning model of the response to palbociclib, a CDK4/6i, based on a reference map of multiprotein assemblies in cancer." (PMID 38443662, 2024). "The intrinsic resistance mechanisms of CDK4/6i and their application to additional cancer types warrant further investigation." (PMID 38424044, 2024). "We collected data from 32 patients with HR+/HER2– MBC treated with anlotinib plus chemotherapy after progressing on CDK4/6i at Jiangsu Cancer Hospital from March 2020 to October 2023." (PMID 39742382, 2024). "Targeting cell cycle regulators, such as CDKs, can be a valuable strategy to stop cancer cell proliferation and induce cell death, as proved by the improvement in the treatment of breast cancer using CDK4/6 inhibitors." (PMID 38473265, 2024). "The activation of cell cycle progression in cancer cells renders CDK4/6 inhibition-based cell cycle arrest a potent therapeutic strategy for cancer treatment." (PMID 38773495, 2024). "The CDK4/6-Rb-E2F axis, which is fundamental for the transition of the cell cycle from the G1 to the S phase, is frequently dysregulated in cancer." (PMID 38886784, 2024). "High MYC expression activates the E3 ligase KLHL42, which is responsible for pRB1 ubiquitination and degradation and subsequently confers resistance to CDK4/6i to cancer cells." (PMID 38424044, 2024). "The inhibition of CDK4/6 activity stops cell division, thus CDK4/6 inhibitors prevent cancer cells from replicating." (PMID 38961854, 2024). "Here, we show that although FOXC1 regulates many cancer hallmarks in TNBC, its function is varied in different cell lines, highlighted by the differential response to CDK4/6 inhibitors upon FOXC1 loss." (PMID 39171293, 2024). "We identify a compound that degrades MYC, A80.2HCl, which induces MYC degradation at nanomolar concentrations, restores pRB1 protein levels and re-establish sensitivity of MYC high-expressing cancer cells to CDK4/6i." (PMID 38424044, 2024). "Ccnd1 triggers the G1–S phase transition in the cell cycle by activating cyclin-dependent kinases (Cdk4 and Cdk6) and enhances the proliferation of cancer cells." (PMID 38251008, 2024). "The fact that CDK4 amplification was frequently observed in MM made scientists discover the role of CDKs and CDKIs in this type of cancer." (PMID 39598629, 2024). "CDK4, a well-characterized cyclin-dependent kinase essential for G1/S phase transition, is frequently dysregulated in various cancers." (PMID 38732173, 2024). "This insight into miRNA involvement complements the therapeutic strategies that incorporate CDK4/6 inhibition, as reduced HIF1α levels further sensitizes tumors to other anti-cancer agents." (PMID 39697237, 2024). "The TGCA samples showed that cancer tissues have a high level of CDK4 mRNA compared to normal tissues." (PMID 38756697, 2024). "Some studies have accounted for predicted and validated gene targets like GATA2, SKI, NTRK3, PAK2, AR, SP1, and CDK4 that describe their involvement in cancer progression." (PMID 38741808, 2024). "There are also distinct cell cycle-independent functions of CDK4 and 6 that promote the development and progression of cancer." (PMID 39598723, 2024).
cancer (continued). "By obstructing the activity of CDK4/6, Ribociclib effectively hampers the transition of cancer cells from the G1 phase to the S phase, thereby impeding their entry into the S phase." (PMID 38998978, 2024). "The CDK4/6i's inhibit the kinase activity of CDK4/6, thereby interrupting the uncontrolled proliferation of cancer cells." (PMID 38817360, 2024). "Ideker and colleagues present NeST-VVN, a deep learning model based on cancer protein assembly data that can be used to predict the response and resistance of cancer cells to CDK4/6 inhibitors." (PMID 38443662, 2024). "Cancer therapy is becoming increasingly promising with the development of effective CDK4/6 inhibitors, such as ribociclib, palbociclib, and abemaciclib, which are already approved." (PMID 39196911, 2024). "Though 45 gene targets for miR-198 are reported across various cancers, the role of only miR-198 mediated regulation of CDK4 is reported in OSCC." (PMID 39697236, 2024). "Studies have reported that the downregulation of the Cyclin D1/CDK4-Rb pathway suppresses cell proliferation and promotes apoptosis of cancer cells." (PMID 39161904, 2024). "Lastly, cancer cells either undergo senescence and apoptosis or develop mechanisms of resistance following CDK4/6 inhibition." (PMID 39461947, 2024). "In this work, we identified CDKL3 as a crucial regulator of cell cycle progression in cancer, phosphorylating Rb to initiate the cell cycle from quiescence and preserving CDK4 to maintain G1 phase advancement." (PMID 38963708, 2024). "P16INK4A expression is inversely associated with RB1 expression in cancer cells, and P16INK4A inhibits CDK4-catalyzed RB1 phosphorylation." (PMID 39351198, 2024). "Among them, the tumor suppressor genes CDKN2A and RB1 are frequently inactivated by copy number deletions or point mutations, whereas the oncogenes CDK4, CDK2, CCND1, and CCNE1 are recurrently amplified in the genomes of some human cancers." (PMID 39351198, 2024). "The cyclin-dependent kinases CDK4 and CDK6 (CDK4/6) govern progression through the early G1 phases of the cell cycle, and therefore they show promising vulnerability to cancer therapy." (PMID 38424044, 2024). "Amplification of cell cycle-encoding genes, including cyclin D, cyclin E, and cyclin-dependent kinase 4 (CDK4), can also occur in certain types of cancer." (PMID 38892280, 2024). "For instance, the overexpression of cyclin D1, observed in various cancers, propels uncontrolled cell proliferation by activating CDK4/6." (PMID 38983782, 2024). "Palbociclib, the first CDK4/6-specific inhibitor, was created in 2004 and has proven effective against a variety of human cancer cell lines." (PMID 38605349, 2024). "With the use of drugs such as palbociclib, ribociclib, and abemaciclib, the development and design of effective CDK4/6 inhibitors are increasingly being proven to be promising cancer treatments." (PMID 39196911, 2024). "CDK4/6 was found to positively regulate the cell cycle by stabilizing and activating forkhead box M1, suppressing ROS levels, and protecting cancer cells from senescence." (PMID 39791714, 2024). "Together, this demonstrates why CDK4/6 inhibitors, and any other anti-cancer drugs that arrest the cell cycle but permit continued cell growth, must now be re-screened against a wide-range of cell types using an appropriate proliferation assay." (PMID 38438376, 2024). "In various cancers, the overexpression or amplification of CDK4 has been observed, promoting uncontrolled cell proliferation and tumorigenesis." (PMID 38195537, 2024). "Although the use of CDK4/6 inhibitors has improved PFS in patients with hormone receptor-positive, HER2−breast cancer, studies have shown that resistance pathways can lead cells to be insensitive to CDK4/6 inhibitors, leading to continued cell proliferation." (PMID 38540112, 2024).
cancer (continued). "In summary, a deepened understanding of the metabolic roles of CDK4/6 will open up avenues for the diagnosis of and metabolic interventions against KSHV malignancies and cancers with dysregulated Cyclin D/CDK4/CDK6 activities." (PMID 38365882, 2024). "Further, studies demonstrate that CDK4/6 inhibitors, such as palbociclib, synergize with HSP90 inhibitors to reduce HIF1α levels and suppress cancer cell viability, even in Rb-deficient tumors." (PMID 39697237, 2024). "Expression levels of CDK-4/-6 are notably elevated in various human cancers, including ovarian cancer, where its expression is inversely related to patient prognosis." (PMID 38611854, 2024). "Our findings suggest that MAP3K3 is a promising target for alleviating drug resistance and that combination treatment with ponatinib with inhibitors of BRAF or CDK4/6 should be further tested as a YAP-targeting strategy in cancer treatment." (PMID 38622197, 2024). "In cancer cells, cyclin D–CDK4/6-dependent phosphorylation of speckle-type POZ protein (SPOP)/Cullin-3 ubiquitin ligase complex destabilizes PD-L1 via proteasome-mediated degradation, but inhibition of CDK4/6 significantly elevates PD-L1 level." (PMID 39103548, 2024). "This last observation suggests that UBR5 inhibition can strengthen the efficacy of Cdk4/6 inhibitor–based cancer therapies." (PMID 39441926, 2024). "Inactivation of the inhibitory gene results in the indirect enhancement of CDK4/6 activity, increasing the sensitivity threshold of cancer cells to CDK4/6 inhibitors, which induces drug resistance." (PMID 39544302, 2024). "We found that CDK4/6i‐induced senescent cancer cells induced strong expression of SASP and ligands related to an anti‐tumorigenic immunity, which was comparable with that induced by DNA‐damaging agent‐induced senescence." (PMID 37854019, 2024). "Studies showed that human epidermal growth factor receptor (HER), SHP-2, mammalian target of rapamycin (mTOR), and cyclin-dependent kinase 4/cyclin-dependent kinase 6 (CDK4/CDK6) inhibitors improved adagrasib efficacy in KRAS G12C-mutant cancers." (PMID 38397927, 2024). "In multiple preclinical studies, CDK4/6is can induce the development of the senescence-like progress imposed by cell-cycle arrest in cancer cells." (PMID 39593745, 2024). "Previous studies have reported that down-regulation of CDKN1A is not only related to the uncontrolled proliferation of cancer cells but also responsible for the resistance of some cell cycle-specific drugs such as CDK4/6 inhibitors and paclitaxel." (PMID 39268503, 2024). "In this regard, similar to other potentially common essential cancer targets such as CDK4/6 and MEK kinases, further pharmacodynamic and toxicity considerations will need to be assessed for SHH-MB." (PMID 39107797, 2024). "Specifically, cancers such as breast (selective estrogen receptor modulators, aromatase inhibitors, CDK4/6 inhibitors), prostate (androgen biosynthesis inhibitors), and lung (TKIs) have highly effective oral therapies." (PMID 38568688, 2024). "LY3009120 or combinations with CDK4/6-inhibitors such as abemaciclib have shown stronger anti-tumor effects with BRAF-mutant cancer cells than cancer cell lines with various NRAS genotypes." (PMID 38397192, 2024). "In cancer cells, the CDK4/6–cyclin D1-Rb1-E2F axis is regarded as the most dysregulated cell cycle pathway." (PMID 38473336, 2024). "Recent studies suggest that CDK4/6 inhibitors influence apoptotic responses, differentiation, and cancer cell immunogenicity." (PMID 39196911, 2024). "The FDA has approved CDK4/6 inhibitors, and their effectiveness in various cancers has been validated both in preclinical and clinical studies." (PMID 39196911, 2024).